MTND5P25 (MT-ND5 pseudogene 25)
Gene: Unprocessed pseudogene on chromosome 2 (201,212,283 to 201,213,081, reverse strand). Ensembl gene ENSG00000227348.
Diseases named in the same sentence as MTND5P25 in open-access papers:
MTND5P25 is named in the same sentence as 1 disease in open-access papers, as found by Europe PMC text mining. Sharing a sentence is not in itself a finding about the gene and the disease. The quoted sentences say what the papers report.
cancer (1 paper, 2021). A tumor composed of atypical neoplastic, often pleomorphic cells that invade other tissues. "Of these genes, six lncRNA (AL360091.3, AL360175.1, AC025254.1, AC093801.1, AC092354.1 and AC016722.1); four pseudogenes (RBM22P2, AC073324.1, OR1X1P, RPL7P52 and MTND5P25) and coding SLC36A2 and SDS and have not previously been shown to be transcripts in cancer." (PMID 34026616, 2021).